CDH13 (cadherin 13)
Diseases named in the same sentence as CDH13 in open-access papers (continued):
Sharing a sentence is not in itself a finding about the gene and the disease.
coronary artery disease (7 papers, 2015 to 2025). "Decreased levels of cadherin-13 in plasma are associated with increased severity of coronary artery disease and a higher risk of acute coronary syndrome." (PMID 38791465, 2024). "These genes included Cdh13 and Lpl from Cluster 1; Nfia, Col4a1 and Serpinh1 from Cluster 2; Arhgef12, Col4a2, Scarb1 and Cst3 from Cluster 3; Pecam1 and Aldh2 from Cluster 4, providing plausible molecular basis for the inextricable causal link between age and coronary artery disease." (PMID 35615560, 2022). "SNPs in CDH13 have been associated with total cholesterol and LDL levels, coronary artery disease (CAD), hypertension and blood pressure, hyperlipidemia and myocardial infarction, metabolic syndrome and preeclampsia." (PMID 25543204, 2015). "The methylation profiling of the CDH13 promoter in the HYPEST/CADCZ (HYPertension in ESTonia/Coronary Artery Disease in Czech) study sample (n = 358) resulted in the methylation levels of 46 CpG sites/units within 1,162 bp of its CpG island and flanking 361 bp 5′ upstream region." (PMID 25543204, 2015). "Another candidate is miR-584-5p, described as a marker of pathological states in coronary artery disease (CAD), which was demonstrated to target CDH13." (PMID 40649905, 2025). "Resequencing and EpiTYPERTM assay were applied for the HYPertension in ESTonia/Coronary Artery Disease in Czech (HYPEST/CADCZ; n = 358) samples to identify CDH13 promoter SNPs acting as methylation Quantitative Trait Loci (meQTLs) and to investigate their associations with CMT." (PMID 25543204, 2015).
diabetes (7 papers, 2015 to 2025). "The cHMW adiponectin levels were increased significantly beyond 100 years of age, were negatively associated with diabetes prevalence, and were associated with SNVs in CDH13 (p=2.21 × 10-22) and ADIPOQ (p=5.72 × 10-7)." (PMID 37768324, 2023). "Besides, it was found that CDH13 rs7193788 had higher risks for IS in patients with diabetes." (PMID 41165008, 2025).
prostate carcinoma (7 papers, 2009 to 2024). A carcinoma that arises from epithelial cells of the prostate gland. "Some hypermethylated genes in prostate cancer are also hypermethylated in other types of cancer, such as p16 in colorectal cancer, gastric cancer, and leukemia; and CDH13, APC, and CDH1 in leukemia." (PMID 37234978, 2023). "CDH13 is widely expressed in the brain and cardiovascular system but is absent or strongly suppressed in a number of cancer cell lines, such as lung, ovarian, cervical and prostate cancer 34-37." (PMID 32127937, 2020).
squamous cell carcinoma (7 papers, 2007 to 2025). A carcinoma arising from squamous epithelial cells. "Squamous cell carcinomas revealed frequent promoter methylation, that is in >40% of cases, of CDH13 (nine out of 16: 56.3%), DAPK1 (nine out of 16: 56.3%), MGMT (15 out of 16: 93.8%) and CADM1 (nine out of 16: 56.3%)." (PMID 17971771, 2007). "The results showed two hypomethylated genes (CDKN2A and MGMT) and three hypermethylated genes (CDH13, RUNX3, APC) in adenocarcinomas compared with squamous cell carcinomas, with higher sensitivity and specificity values of CDH13 and APC." (PMID 30917582, 2019). "Overexpression of CDH13 has also been shown to increase ITGβ1 expression in squamous carcinoma cells, even though a direct interaction has not been reported." (PMID 33972691, 2022).
attention deficit-hyperactivity disorder (6 papers, 2012 to 2022). A disorder characterized by a marked pattern of inattention and/or hyperactivity-impulsivity that is inconsistent with developmental level and clearly interferes with functioning in at least two settings (e.g. at home and at school). "The gene coding for Cadherin 13 (CDH13) was found among the top hits in several genome-wide association studies (GWAS) for attention-deficit/hyperactivity disorder (ADHD)." (PMID 34573337, 2021). "Recently, CDH13 has been associated with hyperactive/impulse symptoms in attention deficit hyperactive disorder (ADHD)." (PMID 28386779, 2017). "CDH13 has also been implicated in attention deficit hyperactivity disorder (ADHD) at multiple SNPs, including rs11646411 and rs6565113." (PMID 22952603, 2012). "Previous studies have showed that CDH13 may be a promising candidate gene for Attention Deficit/Hyperactivity Disorder (ADHD) and plays a central role in the regulation of brain networks." (PMID 30221000, 2018).
autism spectrum disorder (6 papers, 2015 to 2024). A spectrum of developmental disorders that includes autism, and Asperger syndrome. "Disruption of CDH13 by rare de novo and inherited deletions was linked to autism spectrum disorders; Van der Burgt, personal communication)." (PMID 29018333, 2017). "Other important genes identified by gene-based GWASs include neural adhesion molecules CNTN4 (p = 3.88e-9) on chr3p26.3-p26.2 which has been linked to autism spectrum disorders, PCSK5(p = 2.88e-11) on chr9q21.13, and CDH13 (p = 4.19e-8) on chr16q23.3) and TMEM132 (p = 2.18e-8) on chr17q12." (PMID 34868193, 2021). "Dysregulation of CDH13 expression may thus contribute to alterations in this system of neurotransmission, impacting cognitive function, which is frequently impaired in neurodevelopmental disorders including attention-deficit/hyperactivity and autism spectrum disorders." (PMID 29018333, 2017).
endometrial cancer (5 papers, 2006 to 2025). Primary or metastatic malignant neoplasm involving the endometrium (mucous membrane that lines the endometrial cavity). "Incidence for APC, CDH13, p16 and hMLH1 in endometrial cancer was 41.7%, 35.0%, 25.0% and 13.3% respectively." (PMID 16928264, 2006). "Thus, we have shown that an assessment of the CDO1 and CDH13 gene methylation levels in endometrial specimens from patients with endometrial cancer (IA stage G1) can predict the treatment outcome." (PMID 38732110, 2024). "Objective of the study: To determine CDO1, PITX2, and CDH13 gene methylation levels in early endometrial cancer and atypical hyperplasia specimens obtained before organ-preserving treatment in the patients with adequate response and with insufficient response to hormonal treatment." (PMID 38732110, 2024). "The analysis of the treatment outcomes for endometrial cancer IA stage G1 showed that the methylation level of CDO1 and CDH13 genes may help to predict a positive treatment outcome (complete response) with high accuracy (AUC = 0.96)." (PMID 38732110, 2024).
Insulin resistance (5 papers, 2014 to 2021). Increased resistance towards insulin, that is, diminished effectiveness of insulin in reducing blood glucose levels. "In addition, the CDH13 genotypes exhibited a significant association with insulin resistance, metabolic syndrome and related metabolic phenotypes." (PMID 25875811, 2015). "Perhaps most importantly, cadherin-13 (also known as T-cadherin) has been demonstrated to be a regulatory component of insulin signaling endothelial cells, and may in fact be a determinant of the development of endothelial insulin resistance." (PMID 32596266, 2020).
metabolic syndrome (5 papers, 2015 to 2021). A cluster of metabolic risk factors for CARDIOVASCULAR DISEASES and TYPE 2 DIABETES MELLITUS. "In our recent study, adiponectin levels also acted as suppressors for the association between CDH13 SNPs and metabolic syndrome and metabolic phenotypes." (PMID 27313400, 2016). "In the present study, we used mediation analysis to further elucidate the relationships of CDH13 gene variants with circulating adiponectin levels, metabolic phenotypes, and metabolic syndrome." (PMID 25875811, 2015). "After mediation analysis, our data showed the CDH13 rs12051272 polymorphism to be the most significant CDH13 variant associated with metabolic phenotypes and metabolic syndrome in Han Chinese people in Taiwan." (PMID 26600672, 2015). "The mediation analysis further revealed a suppression effect of the adiponectin levels on the association between CDH13 genotypes and metabolic syndrome and its related phenotypes (Sobel test; all P < 0.001)." (PMID 25875811, 2015). "The genetic polymorphisms at the CDH13 locus independently affect the adiponectin levels, whereas the adiponectin levels exhibit a suppressive effect on the association between CDH13 locus variants and various metabolic phenotypes and metabolic syndrome." (PMID 25875811, 2015). "Association of CDH13 rs12051272 genotypes, serum adiponectin levels and metabolic syndrome-related phenotypes." (PMID 25875811, 2015). "In conclusion, our data reveal a significant association of CDH13 locus variants with not only adiponectin levels but also metabolic phenotypes and metabolic syndrome." (PMID 25875811, 2015). "Overall, a complex relationship was observed among the CDH13 locus variants and metabolic syndrome, and these results suggested that the CDH13 gene variants play a crucial role in the genetic determinants of metabolic syndrome and related metabolic phenotypes." (PMID 25875811, 2015). "This hypothesis can be supported by the mediation analysis performed in this study, which indicates that adiponectin acts as a suppressor of the association between the CDH13 genotypes/haplotypes and the various metabolic phenotypes and metabolic syndrome." (PMID 25875811, 2015). "In addition, these results provide further evidence of the association between the CDH13 gene variants and the risks of metabolic syndrome and atherosclerotic cardiovascular disease." (PMID 25875811, 2015).
osteosarcoma (5 papers, 2015 to 2025). A usually aggressive malignant bone-forming mesenchymal neoplasm, predominantly affecting adolescents and young adults. "In osteosarcoma cells, CDH13 expression was modulated by estradiol and progesterone." (PMID 33407434, 2021).
schizophrenia (5 papers, 2021 to 2025). A major psychotic disorder characterized by abnormalities in the perception or expression of reality. "Our TWAS also identified genes previously associated with cognitive domains, neuropathology, and psychiatric illness, including reading-related skills and neural structures (SEMA6D and SETBP1), working memory tasks (CDH13), and Schizophrenia (HP, C18orf1, and TMEM180)." (PMID 40141087, 2025). "In addition to being associated with MDD, genetic polymorphism in CDH13 was also linked with other mental health phenotypes, including substance abuse, smoking cessation outcomes, ADHD, violent behavior, schizophrenia, and bipolar disorder symptoms." (PMID 36011346, 2022).
triple-negative breast carcinoma (5 papers, 2007 to 2024). An invasive breast carcinoma which is negative for expression of estrogen receptor (ER), progesterone receptor (PR), and human epidermal growth factor receptor 2 (HER2). "We observed that triple-negative breast cancers tended to have increased CDH13 methylation (p = 0.044) and a decreased methylation of the RASSF1A (p<0.02) and SFRP1 (p<0.05) genes when compared with other subtypes." (PMID 22701537, 2012). "The subset of triple-negative breast cancers (in other words, those with negative ER, PR, and HER-2/neu status) was positively associated with the methylation of the RIL/CDH13 panel and negatively associated with the HIN-1/RASSF1A panel." (PMID 17764565, 2007). "While changes such as the upregulation of ADAM19 in the invading subpopulation may be shared among the triple negative breast cancer cells tested in this study, other genes, such as BEX1 and CDH13, were seen in some samples but not in others." (PMID 32238832, 2020). "Interestingly, we found that triple-negative breast cancers (in other words, those with negative ER, PR, and HER-2/neu status) were positively correlated to methylation of the RIL/CDH13 panel and negatively correlated to methylation of the HIN-1/RASSFIA panel." (PMID 17764565, 2007).
colon carcinoma (4 papers, 2004 to 2014). "Recently, the loss of CDH13 (T-cadherin, H-cadherin) gene expression accompanied by CDH13 promoter methylation was identified in colon cancers." (PMID 15292927, 2004). "Recently, the loss of expression of CDH13 (T-cadherin, H-cadherin) accompanied by CDH13 promoter methylation was reported in colon cancers." (PMID 15292927, 2004). "Moreover, CDH13 methylation was detected in 17 of 35 primary colon cancers, suggesting that CDH13 is a common target for methylation and epigenetic gene silencing in colon cancer and qualifies as a potential colon cancer suppressor gene." (PMID 15292927, 2004). "In this report, all colon cancer cell lines that lacked CDH13 gene expression demonstrated methylation of CpG sites within the putative CDH13 promoter." (PMID 15292927, 2004).
pancreatic cancer (4 papers, 2020 to 2024). "Nonetheless, CDH13 down-regulation by aberrant methylation in the CpG island of its promoter is associated with colorectal, NSCLC, and pancreatic cancer." (PMID 33407434, 2021). "CDH13 repression due to aberrant CDH13 promoter methylation has been associated with colorectal, NSCLC, and pancreatic cancer." (PMID 33407434, 2021). "Although the CDH13 promoter is frequently hypermethylated in pancreatic cancer (PC), the direct impact of CDH13 on PC is unknown." (PMID 32127937, 2020). "The results reveal hypermethylation of the CDH13 promoter in cancers such as kidney renal papillary cell carcinoma (KIRP), pancreatic cancer, uveal melanoma (UM) and acute myeloid leukemia (AML) and sarcoma." (PMID 39179585, 2024). "Genes coexpressed with CDH13 were correlated with “Development_Regulation of epithelial-to-mesenchymal transition (EMT)”, “Role of stellate cells in progression of pancreatic cancer”, and “Cell adhesion ECM remodeling”." (PMID 36315446, 2022).
adenoma (3 papers, 2004 to 2016). A neoplasm arising from the epithelium. "Moreover, some of them, such as APC and RUNX3 were significantly more frequently methylated in patients with UC and cancer compared to patients with non inflammatory adenocarcinoma and CDH13 was more frequently methylated in patients with UC and dysplasia compared to those with adenoma." (PMID 26862732, 2016). "ESR1 has been shown to occur in histologically normal colon epithelium in an age dependent fashion, CDH13 is also frequently methylated in CRC and seems to be correlated with the adenoma-carcinoma transition, like other genes with methylation frequencies > 30% (CDKN2B, RASSF1, RARB, APC and TIMP3)." (PMID 25091577, 2014).
B cell lymphomas (3 papers, 2018 to 2023). "Cell adhesion and recognition are mediated by H-cadherin (CDH13), and one of the interesting in vitro studies showed decreased expression of CDH13 in B cell lymphomas, which was owed to aberrant methylation on the promoter region of CDH13." (PMID 36765652, 2023). "CDH13 is not involved in cell-cell adhesion, but protects vascular endothelial cells from apoptosis due to oxidative stress and is found to be hypermethylated in myeloid leukemia, B-cell lymphomas among several other cancers." (PMID 30134812, 2018).
bladder cancer (3 papers, 2016 to 2018). "Results from 4 studies comparing a total of 169 high-grade patients and 284 low-grade patients showed that CDH13 methylation was significantly associated with high-grade bladder cancer (OR = 2.22, 95 % CI = 1.72–6.80, P < 0.001)." (PMID 27578166, 2016). "A significant association was found between CDH13 methylation levels and bladder cancer (OR = 21.71, P < 0.001)." (PMID 27578166, 2016). "The results of subgroup analyses based on sample type suggested that CDH13 methylation was significantly associated with bladder cancer risk in both the tissue and the urine (OR = 53.94, P < 0.001; OR = 7.71, P < 0.001; respectively)." (PMID 27578166, 2016). "Our results revealed that CDH13 methylation was significantly associated with high-grade bladder cancer, multiple bladder cancer and muscle invasive bladder cancer (OR = 2.22, P < 0.001; OR = 1.45, P = 0.032; OR = 3.42, P < 0.001; respectively)." (PMID 27578166, 2016). "CDH13 methylation status was significantly associated with high-grade (grade 3) bladder cancer (OR = 2.22, P < 0.001)." (PMID 27578166, 2016). "Results from 5 studies analyzing a total of 319 bladder cancer patients with multiple tumors and 281 bladder cancer patients with single tumors demonstrated that methylated CDH13 was significantly associated with patients harboring multiple tumors (OR = 1.45, 95 % CI = 1.03–2.04, P = 0.032)." (PMID 27578166, 2016). "However, the association between CDH13 promoter methylation and bladder cancer remains to be clarified." (PMID 27578166, 2016). "Specifically, transfection of CDH13 siRNA constructs into a human bladder carcinoma cell line significantly promoted the migration of these cells compared with controls." (PMID 28386779, 2017). "In this study, a meta-analysis was conducted to evaluate the effect of CDH13 methylation on the clinicopathological features of patients with bladder cancer." (PMID 27578166, 2016). "Our findings indicated that CDH13 promoter methylation was a very useful biomarker that can predict the recurrence of bladder cancer." (PMID 27578166, 2016). "The levels of methylated CDH13 were significantly higher in bladder cancer consisting of multiple tumors than in bladder cancer consisting of a single tumor (OR = 1.45, P = 0.032)." (PMID 27578166, 2016). "Thus, Cadherin 13 was considered an important tumor suppressor in colorectal, lung, breast, ovarian and bladder cancers." (PMID 29416663, 2018). "However, the clinical effect of the CDH13 methylation status of patients with bladder cancer remains to be clarified." (PMID 27578166, 2016). "Our study indicates that CDH13 methylation may play a key role in the initiation and progression of bladder cancer, especially among Asian populations." (PMID 27578166, 2016). "In addition, CDH13 methylation has the potential to become a useful biomarker for the clinical screening of bladder cancer in the urine." (PMID 27578166, 2016). "CDH13 promoter methylation has been reported in some human cancers including bladder cancer." (PMID 27578166, 2016). "In addition, CDH13 methylation has the potential to be a useful biomarker for bladder cancer screening in urine samples and to be a prognostic biomarker in the clinic." (PMID 27578166, 2016). "The pooled OR from 5 studies including 174 advanced bladder cancer patients and 345 early stage bladder cancer patients indicated that CDH13 methylation was significantly higher in advanced stage tumors than in early stage tumors (OR = 3.42, 95 % CI = 1.72–6.80, P < 0.001)." (PMID 27578166, 2016). "Our study indicates that CDH13 methylation may play an important role in the carcinogenesis, development and progression of bladder cancer." (PMID 27578166, 2016).
bladder cancer (continued). "The findings of the current study showed that CDH13 promoter methylation was significantly higher in bladder cancer patients than in non-tumor control samples (OR = 21.71, P < 0.001), suggesting that the methylation of CDH13 may be involved in the development of bladder cancer." (PMID 27578166, 2016). "The OR value of CDH13 methylation in bladder cancer patients compared with non-tumor controls was 21.71 (95 % CI: 9.83–47.94, P < 0.001); this analysis included 920 bladder cancer patients and 265 controls." (PMID 27578166, 2016). "However, the potential of CDH13 gene methylation to be a biomarker for bladder cancer has not yet been evaluated." (PMID 27578166, 2016).
epilepsy (3 papers, 2018 to 2024). A brain disorder characterized by episodes of abnormally increased neuronal discharge resulting in transient episodes of sensory or motor neurological dysfunction, or psychic dysfunction. "We discovered the combinatorial expression of Protocadherin-19(Pcdh19), a protein involved inPCDH19-clustering epilepsy, with Pcdh1, Pcdh9 or Cadherin 13 (Cdh13) in excitatory neurons." (PMID 38629124, 2024). "Other genes with CNV losses that have an indirect relation to epilepsy are RYR3, CDH13, PCDH9, and LRRC55." (PMID 33557955, 2021).